IL6 (interleukin 6)
Diseases named in the same sentence as IL6 in open-access papers (continued):
Sharing a sentence is not in itself a finding about the gene and the disease.
syphilis (15 papers, 2015 to 2024). A contagious bacterial infection caused by the spirochete Treponema pallidum. "IL-6 dysregulation contributes to chronic inflammation in certain conditions Therefore, we hypothesize that overproduction of IL-6 plays a crucial role in the inflammatory responses caused by T. pallidum, thus contributing to the pathogenesis of syphilis." (PMID 31293985, 2019). "Our study first identified dramatically decreased miR-216a-5p in plasma of syphilis patients compared with the healthy control, which was negatively correlated with the expression of inflammatory cytokines, including IL-1β, IL-6, and TNF-α." (PMID 31358689, 2019). "In the present study, we first identified that miR-216a-5p decreased in the plasma of patients with syphilis compared with the healthy control, which was negatively correlated with levels of inflammatory cytokines such as IL-1β, IL-6, and TNF-α." (PMID 31358689, 2019). "Our results are supported by previous research showing increased secretion of IL-6 from human dermal vascular smooth muscle cells (HDVSMCs) exposed to T. pallidum, and elevated serum concentrations of IL-6 in individuals diagnosed with syphilis." (PMID 37795301, 2023). "T. pallidum lipoproteins and flagellin have been reported to increase the expression of IL-6 in monocytes and may play an important role in the inflammatory process in syphilis." (PMID 31293985, 2019). "IL‐6 in patients with KS and syphilis were significantly lower at baseline." (PMID 29671462, 2018). "Some scholars found that such cytokines IL-6, IL-10, TNF-α are involved in the pathogenesis and development of syphilis, with the progression of the disease cellular immune function being somewhat suppressed." (PMID 35669916, 2022). "The overexpression of miR-101-3p inhibits the expression of IL-6 and TNF-а in an article about syphilis, which explains the link between miR-101-3p and inflammation." (PMID 35506305, 2022). "A study found that the levels of IL-1β, IL-6, and TNF-α were elevated in serum collected from syphilis patients." (PMID 33282751, 2020). "The results showed that the miR-216a-5p expression level was negatively correlated with the expression of inflammatory cytokines IL-1β, IL-6, and TNF-α, indicating the potential function of miR-216a-5p in syphilis progression." (PMID 31358689, 2019). "In accordance with previous studies, the inflammatory cytokines IL-1β, IL-6, and TNF-α were found to be significantly up-regulated in plasma of syphilis patients compared with the healthy controls." (PMID 31358689, 2019). "To investigate possible inflammatory mechanisms connecting CMV shedding and acquisition of syphilis, we measured levels of selected cytokines and chemokines (i.e., MCP-1, IL-6, TNF-α, Interferon-γ, RANTES, and IP-10) in seminal plasma." (PMID 26061824, 2015). "The reaction is associated with an increase in circulating levels of TNF-α, interleukin-6 (IL-6), and IL-8 and has been reported more frequently among HIV-infected early syphilis patients compared to non-HIV infected controls." (PMID 31493128, 2019). "Moreover, there was a negative correlation between the levels of miR-216a-5p and inflammatory cytokines such as IL-1β, IL-6, and TNF-α, which were dramatically increased in syphilis patients." (PMID 31358689, 2019). "We prospectively recruited all patients with a new diagnosis of syphilis and tested their plasma for IFNα, IFNγ, IL-1β, IL-12p40, IL-12p70, IP-10, MCP-1, MIP-1α, MIP-1β, IL-4, IL-5, IL-6, IL-7, IL-8, IL-10 and IL-17A at baseline pre-treatment and 6 months following therapy." (PMID 28143443, 2017). "The median levels of IL‐6, IL‐10 and IFN‐ gamma at baseline and at week 12, in patients with and without syphilis, without any co‐infection and with IADE are shown." (PMID 29671462, 2018).
syphilis (continued). "In comparison with the trace CSF levels of all 4 cytokines in non-neurotic syphilis, both non-HIV and HIV-positive CM and TBM significantly increased the CSF IL-6 and IL-10 levels, and TBM considerably increased the CSF IFN-γ and slightly increased the IL-17 levels." (PMID 35720334, 2022).
acute lymphoblastic leukemia (14 papers, 2011 to 2026). Leukemia with an acute onset, characterized by the presence of lymphoblasts in the bone marrow and the peripheral blood. "This novel partner cell line is a tri-hybrid of IL-4 secreting Th2 lymphoblast derived from a patient with acute lymphoblastic leukaemia (T), CD20+ B lymphoblast, also derived from a patient with acute lymphoblastic leukaemia (W), and IL-6 secreting peripheral blood-derived CD14+ monocyte (M)." (PMID 22373339, 2011). "We have previously shown that FAB subgroups M4 and M5 are characterized by the highest LDL degradation rate compared to FAB-M1-3 and acute lymphoblastic leukemia which is in agreement with reports showing that TNF-α, IL-6, IL-8, and IL-18 are over-expressed and secreted in these subgroups." (PMID 28488049, 2017).
alcoholic hepatitis (14 papers, 2009 to 2025). Acute hepatitis resulting from ingestion of alcohol. "More recently, IL-6, IL-22, interferon-α2, soluble TNF receptor 1, lipocalin-2, and α-fetoprotein have been linked to mortality within 28 days in patients with severe alcoholic hepatitis, and IL-6, IL-13, and endotoxin levels to mortality within 90 days." (PMID 39273468, 2024). "The plasma concentrations of inflammatory cytokines such as TNF-α, IL-1, IL-6 and IL-8 are high in patients with alcoholic hepatitis." (PMID 28403148, 2017). "Clinical studies have shown that the plasma endotoxin and hepatic cytokines including TNF-α, IL-6, and IL-8 were increased in patients with alcoholic hepatitis, while declined in the recovery phase." (PMID 26501337, 2015). "Additionally, it has been reported that both TNF-α and IL-6 are substantially elevated in the circulation of patients with acute alcoholic hepatitis." (PMID 36144575, 2022). "In the MOD group, intervention with COST and COSM led to a reduction in serum levels of the inflammatory cytokines TNF-α, IL-1β, and IL-6 in the mice, suggesting that both compounds may ameliorate alcoholic hepatitis, albeit with COSM exhibiting slightly superior efficacy compared to COST." (PMID 40137320, 2025). "In patients with alcoholic hepatitis, there were observed increasing levels of TNF-α, IL-6, IL-8, and IL-18 pro-inflammatory cytokines." (PMID 38473721, 2024). "Animal models of ALD and patients with alcoholic hepatitis showed an increase in the TNF-α, IL-1, and IL-6 levels." (PMID 32423176, 2020).
Anosmia (14 papers, 2021 to 2025). An inability to perceive odors. "This improvement was associated with a downregulation of IL-1β and IL-6 mRNA in the brain ́s prefrontal cortex, and it was impaired by anosmia induction with methimazole." (PMID 37187754, 2023). "Group 1 exhibited statistically significant improvements in fever, cough, diarrhea, as well as NLR, IL-6, and CRP by 14 days, and in anosmia, loss of taste, shortness of breath, general weakness, and headache by 60 days." (PMID 39355453, 2024). "The mechanism used by these cytokines, in particular IL-6, to produce anosmia is not fully understood." (PMID 33824716, 2021). "In addition, persistent inflammation evidenced by elevated levels of interleukin 6 (IL-6), type I interferon (IFN), and C-X-C motif chemokine ligand 10 (CXCL10) within the olfactory epithelium, secondary to invasion, appears to contribute to long-standing anosmia." (PMID 36899952, 2023).
autoimmune uveitis (14 papers, 2010 to 2025). An autoimmune form of uveitis (disease). "TNF-α and IL-6 are indeed recognized as important mediators of ocular inflammation in the early stages of autoimmune uveitis." (PMID 39684616, 2024). "Intravitreal administration of anti-IL-6 treatment notably mitigates experimental autoimmune uveitis in mice, both functionally and clinically." (PMID 39497001, 2024). "It is worth noting that IL-2, IL-6, IL-13, IL-18, IFN-γ, and TNF-α were significantly higher in the aqueous humor of children with JIA-associated autoimmune uveitis." (PMID 36969183, 2023). "The levels of IL-6 are elevated in the serum, plasma, tear, PBMCs, aqueous humor (AqH), and vitreous fluid of patients with active autoimmune uveitis." (PMID 33816637, 2021). "Th17 cells, and their related cytokines, such as IL-6 and IL-17, are likely to be more important inflammatory mediators in autoimmune uveitis." (PMID 32380695, 2020). "i.e., IL-6 blockage has been proposed for other IL-6-mediated ocular diseases, such as autoimmune uveitis, and in experimental corneal burns." (PMID 25741769, 2015). "Increased levels of IL-6 were found in aqueous humour in a murine model of experimental autoimmune uveitis demonstrating an increased local production at disease onset." (PMID 20467456, 2010). "Injecting an anti-IL-6 antibody into the eye reduced experimental autoimmune uveitis in mice." (PMID 39839649, 2024). "The proinflammatory role of IL-6 in autoimmune uveitis has been widely described." (PMID 33816637, 2021). "Therefore, treatment targeting the IL-6 and IL-6R has emerged as an innovative therapeutic approach for autoimmune uveitis." (PMID 33816637, 2021). "In an autoimmune uveitis murine model, AhR was shown to regulate immune responses through STAT/NF-κB signaling and the subsequent production of pro-inflammatory cytokines, including TNF-α, IL-6, and IL-1β." (PMID 41300485, 2025). "In addition to mitochondria-targeted antioxidant therapy, our results suggest a number of potential therapeutic options for autoimmune uveitis, including blockade of TNF-α/IL-6 and PAF signaling, inhibition of prostaglandin synthesis or DHA and ascorbic acid supplementation." (PMID 39684616, 2024).
bronchiolitis (14 papers, 2017 to 2025). Inflammation of the bronchioles characterized by swelling of the bronchioles and mucus accumulation. "Our results indicate that bacterial sRNAs associated with bronchiolitis result in the upregulation of IL-8 and IL-6 pathways in RSV-only cases compared to RV-only cases." (PMID 38410509, 2024). "Other studies performed in children with bronchiolitis caused by hRSV infection showed that high IL-6 levels in nasal samples and BALF correlated with the need for ventilation and with a higher degree of hypoxia." (PMID 31214165, 2019). "sRNAs are known to downregulate their mRNA target, we found that, compared to those associated with RV-only bronchiolitis, sRNAs associated with RSV-only bronchiolitis may relatively activate the IL-6 and IL-8 pathways and relatively inhibit the IL-17A pathway." (PMID 38410509, 2024). "Elevated IL-6 in RSV-infected cells is consistent with clinical observations that IL-6 levels are detectable in respiratory secretions of infants with RSV bronchiolitis." (PMID 40630640, 2025). "Nonetheless, although the difference was not quite significant, infants with RSV-bronchiolitis trended higher in IL-8 and IL-6 production than those with RV-bronchiolitis." (PMID 38410509, 2024). "IL-8 and IL-6 are two proinflammatory cytokines that have been proposed as potential biomarkers for bronchiolitis severity in several studies." (PMID 38410509, 2024). "This, and Diaz’s findings, are consistent with our predictions that IL-8 and IL-6 signaling may be upregulated in RSV-bronchiolitis and comparatively downregulated by bacteria in RV-bronchiolitis." (PMID 38410509, 2024). "Furthermore, children admitted in hospital with bronchiolitis due to hRSV-infection exhibited higher concentrations of IL-6 in nasal swabs as compared with their older siblings." (PMID 30936869, 2019). "Despite the predicted downregulation of the pathway, IL-6 was a target of sRNAs associated with RSV-only cases, and therefore there was a higher predicted level of IL-6 and subsequent activation of STAT3 in RV-only bronchiolitis comparatively." (PMID 38410509, 2024). "IL-6 signaling was also predicted to be downregulated in RV-only bronchiolitis and upregulated in RSV-only bronchiolitis comparatively (z-score = -4.041; p-value = 0.002)." (PMID 38410509, 2024). "In RV bronchiolitis, there is a predicted relative inhibition of IL-8 and IL-6 signaling compared to RSV bronchiolitis, leading to lower predicted inflammation in RV-bronchiolitis." (PMID 38410509, 2024). "The complexity of the decreased predicted measurement of these cytokines, particularly IL-6, with the predicted activation of their signaling pathway seen in RSV-only bronchiolitis is reflected in the literature." (PMID 38410509, 2024). "In this sense, it has been proposed that elevated levels of IL6, IFNγ and IL10 among others, protect against hypoxia in bronchiolitis." (PMID 36561744, 2022). "Here we show that elevated levels of pro-inflammatory cytokines (IL1β, IL6, TNFα, IL18, IL23), regulatory cytokines (IL10, IL17A) and IFNγ were found in the three bronchiolitis cohorts." (PMID 36561744, 2022). "Pro-inflammatory cytokines IL1β, IL6, TNFα, IL18 and IL23 were increased in the bronchiolitis samples relative to their respective control cohort." (PMID 36561744, 2022). "Our observation of IL-6 upregulation confirms that even in isolated epithelial cells, RSV alone is sufficient to trigger a strong pro-inflammatory signal, which in an organism would amplify into the full syndrome of bronchiolitis." (PMID 40630640, 2025). "The elevated IL-6 in RSV-infected HEp-2 cells is consistent with numerous in vivo studies where IL-6 is found in nasopharyngeal aspirates and bronchoalveolar fluid of children with RSV bronchiolitis." (PMID 40630640, 2025).
celiac disease (14 papers, 2014 to 2025). An autoimmune genetic disorder with an unknown pattern of inheritance that primarily affects the digestive tract. "Numerous studies have linked IL-6 to the development of celiac disease." (PMID 34895167, 2021). "We have thus examined the hypothesis that villous atrophy in coeliac disease may represent a disorder of pathological matrix expansion in which IL-6 may be implicated, and have additionally studied expression of other components besides IL-6 involved in TH17 pathway responses." (PMID 25198673, 2014). "In celiac disease, IL-6 stimulates acute phase responses and promotes T-helper cell 17 (Th17) differentiation, which leads to tissue injury." (PMID 34895167, 2021). "The present study aimed to evaluate the association between serum levels of interleukin IL-1, IL-6, IL-8 genes as well as interferon (IFN)-γ and the risk of celiac disease (CD)." (PMID 32099611, 2019). "Expression of IL-6 was strongly enhanced within the mucosa of a further 9 children with coeliac disease compared to normal duodenum." (PMID 25198673, 2014). "The mean density of IL-6+ cells within the lamina propria was significantly higher in coeliac disease (104.7±13.1/high power field) compared to normal controls (22.2±16.1, p<0.05)." (PMID 25198673, 2014). "As in other matrix expansion disorders, IL-6 is upregulated and represents a logical target for immunotherapy in patients with coeliac disease refractory to gluten-free diet." (PMID 25198673, 2014). "Increased expression of various potentially matrix-shaping cytokines, including IFN-γ, TNF-α, and IL-6 has been reported in coeliac disease." (PMID 25198673, 2014). "RT-PCR evaluation in matched biopsies also demonstrated marked increase of IL-6 mRNA in coeliac disease compared to controls, with mean expression density 508 vs 68/mm2, normalised to GAPDH 0.68 vs 0.05 (p<0.014)." (PMID 25198673, 2014). "In refractory coeliac disease, where villous atrophy persists despite gluten free diet, mucosal IL-6 expression is further increased and its systemic release enhanced, especially in enteropathy associated T cell lymphoma." (PMID 25198673, 2014). "In IBDs and, in particular, in celiac disease (CeD), IL-6 might trigger the expression, upregulation and secretion of hepcidin in the small intestine, reducing iron efflux and exacerbating defective iron absorption." (PMID 32349426, 2020). "Moreover, integrating analyses of other cytokines (e.g., IL-1, IL-6) and signaling pathways (e.g., RANK/RANKL/OPG axis) may provide a more comprehensive understanding of the mechanisms underlying bone loss in celiac disease." (PMID 41141340, 2025). "IL-6 may represent a pivotal target for immunotherapy in refractory coeliac disease." (PMID 25198673, 2014). "We found, as in celiac disease, strong upregulation of IL-17 signaling and Th17 cell differentiation in EED including induction of IL21, IL6, IL17A IL17F, IL22, IFNG, IL21R, and IL2RA." (PMID 39300663, 2024). "Consistent findings emerged in Spanish children with celiac disease (n = 53) compared to healthy controls (n = 32), where greater UPF intake was not linked to increased IL-6 concentrations." (PMID 41010537, 2025). "With the exception of IL6 and IL10, all serum cytokines analysed at 36 months showed a significant and strong correlation (Pearson’s coefficient r > 0.5) with gluten intake over the second year of life in children who developed celiac disease." (PMID 35354862, 2022). "Excess mucosal IL-6 production has been shown to occur in coeliac disease and to differentiate it from non-coeliac gluten intolerance, in which enhanced innate immune responses also occur but without adaptive changes." (PMID 25198673, 2014). "A dense infiltrate of IL-6+ mononuclear cells was detected in active coeliac disease, also localised to the upper lamina propria, with significantly increased mRNA expression of IL-6 and IL-17A but not IL-23 p19." (PMID 25198673, 2014).
celiac disease (continued). "This speculation would be in line with a previous finding of significantly higher levels for IL-6, IL-13, IL-10, IL-1b, and TNF-α in combination with significantly lower 25(OH)D concentrations in screening-detected celiac disease cases compared with healthy controls." (PMID 34604278, 2021). "One study found that patients with celiac disease who tested positive for tTg-IgA had significantly higher levels of pro-inflammatory cytokines, including IFN-γ, TNF-α, and IL-6, compared to patients without tTg-IgA." (PMID 39697959, 2024).